IL6 (interleukin 6)
Diseases named in the same sentence as IL6 in open-access papers (continued):
Sharing a sentence is not in itself a finding about the gene and the disease.
myeloma (continued). "The other parameters in disease activity and cytokine involved in the pathogenesis of myeloma were IL-6, VEGF, TNF- α, CRP, and LDH." (PMID 35919637, 2022). "Hepcidin, as a one of acute phase proteins, is regulated by interleukin-6 (IL-6), a cytokine inducing MM development (a potential growth factor for myeloma cells)." (PMID 35334593, 2022). "A vicious cycle is established, driven by the secretion by BMSCs of factors that promote the proliferation of myeloma cells (IL-6, IGF-1, transforming growth factor (TGF)-β, and hepatocyte growth factor (HGF)." (PMID 36212502, 2022). "Proliferating myeloma cells likely become more sensitive to DNA-damaging agents in the presence of IL-6." (PMID 35563880, 2022). "Myeloma is a malignancy that is a chronic inflammatory disease, it means there is dysregulation of IL-6." (PMID 35919637, 2022). "In multiple myeloma patients, MIF promoted bone marrow stromal cells to secret the cytokines IL-6 and IL-8, which associated with poor prognosis." (PMID 36387901, 2022). "Myeloma cells can promote erythroblast apoptosis, while cytokines, such as IL-6, impair erythroid maturation and hemoglobin production outside of “iron restriction” pathways." (PMID 35334593, 2022). "In conclusion, adding interleukin 6 to MM cell culture promotes the in vitro growth of myeloma cells and enhances the successful application of FISH technique." (PMID 37521829, 2022). "Mechanisms through which BMSCs decrease the sensitivity of myeloma cells to drug treatments include the secretion of cytokines such as interleukin-6 (IL-6) and vascular endothelial growth factor (VEGF), and cell-to-cell contacts." (PMID 35563880, 2022). "Myeloma and its microenvironment often contain abundant cytokines, such as interleukin (IL)-6, vascular endothelial growth factor (VEGF), and insulin-like growth factor (IGF), which promote the proliferation of myeloma cells." (PMID 35813864, 2022). "Meanwhile, males have higher levels of interleukin-6 (IL-6) than females, which is a pro-inflammatory cytokine that inhibits apoptosis in myeloma cells." (PMID 36358748, 2022). "Expression of RANKL and secretion of IL-6, MIP1α or IL-3 by myeloma cells activates osteoclasts and thereby increases resorption of bone matrix." (PMID 35847862, 2022). "Of interest, a recent study performed CRISPR-mediated deletion of the lncRNA CRNDE and showed decrease in IL6 signaling and proliferation responses in multiple myeloma cells." (PMID 36605450, 2022). "IL-6 produced in the myeloma TME reduces the Th1 response, while an increased Th1/Th2 ratio and high IFN-γ-producing T cells have been reported in the PB of MM patients." (PMID 35172851, 2022). "TGFβ is elaborated by myeloma cells, immune cells, and BM stromal cells, stimulating IL-6 and VEGF secretion, promoting angiogenesis, and supporting myeloma progression." (PMID 36217194, 2022). "As an example, Semenogelin 1 (SEMG1) expression is positively correlated with the presence of interleukins (IL-4 and IL-6) in multiple myeloma cells." (PMID 37529004, 2022). "IL-6 promotes myeloma cell dissemination via downregulation of CD138 expression and increases the vessel wall permeability; therefore, facilitating intravasation of cancer cells." (PMID 35847862, 2022). "Curcumin has an efficacy in improving overall remission and decreasing NF-κB, VEGF, TNF-α, and IL-6 levels in myeloma patients." (PMID 35919637, 2022). "In multiple myeloma cells, MnSOD inhibits the binding of the transcription factor AP-1 to regulate proinflammatory cytokines interleukin 6 (IL-6 or IL6)." (PMID 35017469, 2022). "Multiple Myeloma: curcumin prevents IL-6-induced STAT3 phosphorylation and subsequent STAT3 nu-clear translocation." (PMID 36712505, 2022). "The effects of the anti-IL6 antibody in treating multiple myeloma were tested in NCT00911859 and NCT01484275 trials." (PMID 35453676, 2022). "NF-κB-dependent adhesion of myeloma cells to BMSCs triggers IL-6 secretion to inhibit NK cytotoxicity." (PMID 35172851, 2022).
myeloma (continued). "Moreover, IL-6, in its capacity as a B-cell growth and differentiation factor, was implicated as a driver of neoplastic cell proliferation in hematopoietic dyscrasias including multiple myeloma and Castleman’s disease and other hypergammaglobulinemic conditions such as cardiac myxoma." (PMID 35406728, 2022). "Bone marrow stromal cells (BMSC) secreted IL-6 contributes to drug resistance in myeloma cells through reducing miR-15a expression." (PMID 35760798, 2022). "Adding mitogens such as interleukin 6 (IL6) is known to promote the in vitro growth of myeloma cell lines and enhance the fluorescence in situ hybridization application." (PMID 37521829, 2022). "This happens in part by the ability of osteoblasts to secrete IL-6 when they are in coculture with myeloma cells." (PMID 34890968, 2022). "The main source of IL-6 are stromal cells of the bone marrow, macrophages, osteoblasts, osteoclasts, and even some myeloma cells." (PMID 34205025, 2021). "In agreement with our findings in T-ALL cells, it has been shown that PYK2 mediates chemoresistance of ovarian cancer cells induced by IL-6 and PYK2 has been implicated in myeloma survival and progression." (PMID 34298726, 2021). "IL-6 regulates miR-21 transcription in IL-6-dependent human myeloma cell lines (HMCL) through signal transducers and activators of transcription 3 (STAT3)-related mechanisms." (PMID 34885950, 2021). "In fact, the relationship between IL-6 upregulation and Grb2 activation has been reported in human myeloma and lymphoma." (PMID 33829014, 2021). "Given the myeloma-promoting properties of IL-6, disrupting this pathway appeared to be an attractive approach to improve myeloma control." (PMID 33777050, 2021). "These cytokines recruit osteoblasts, leading to increased cell activity, which produces IL-6, a potent myeloma cell growth factor and bone resorption factor." (PMID 34201396, 2021). "For example, miR-21 is induced by tumor necrosis factor-α (TNF-α) in endothelial cells, by interleukin-1β (IL-1β) in chondrocytes and by interleukin-6 (IL-6) in myeloma cells." (PMID 34222229, 2021). "It has been shown before that IL6 is capable of inducing BCL3 transcription in multiple myeloma cells via STAT3 binding to an enhancer in the BCL3 gene body." (PMID 34422669, 2021). "It has been concluded that the antiproliferative effect of IFN-γ is dependent on IL-6 inhibition, being the central myeloma growth factor." (PMID 33808304, 2021). "IL-6 acts as an antiapoptotic mediator in myeloma cells, whereas in normal cells, its functions seem to mainly involve cell differentiation and development." (PMID 33435539, 2021). "This study suggested that IL-1Ra, as a specific inhibitor of IL-1, induced paracrine IL-6 production and was effective in destroying the proliferative myeloma component." (PMID 35011853, 2021). "It has been shown that IFN-γ inhibits myeloma cell proliferation, on the basis of the IL-6-dependent myeloma cell lines and fresh bone marrow cells." (PMID 33808304, 2021). "BBR (40−160 μmol/L) inhibits cell proliferation and IL-6 secretion in U-266 (human, peripheral blood, multiple myeloma) cells in a time and dosage-dependent manner." (PMID 34885950, 2021). "It has previously been shown that interleukin-6 is positively correlated with pain intensity in advanced, stable multiple myeloma and several other inflammatory cytokines that have been correlated to pain in patients with cancer-induced bone pain." (PMID 33808348, 2021). "The release of both GM-CSF and IL-6 was stimulated by exposure to myeloma light chains, which are a known nephrotoxin." (PMID 34716334, 2021). "At baseline, most Th2 cytokines (i.e., IL-4, IL-5, IL-6, and IL-13) were elevated in the multiple myeloma patients, compared to healthy controls, and most patients had a Th1/Th2 score <1.0, suggesting Th2 dominance." (PMID 34239993, 2021).
myeloma (continued). "A study utilizing preclinical myeloma models demonstrated that siltuximab enhanced melphalan-mediated cytotoxicity; possibly by mitigating melphalan-induced IL-6 production." (PMID 33777050, 2021). "Although some myeloma cells produce IL-6, the main source is the stromal cells of the bone marrow, as well as macrophages, osteoblasts, and osteoclasts." (PMID 34205025, 2021). "β-Caryophyllene suppresses STAT3 activation in human breast and prostate carcinoma and in multiple myeloma cell lines via the inactivation of IL-6." (PMID 34205739, 2021). "A Scutellaria radix component, Baicalein, suppressed myeloma cell survival and proliferation by blocking IκB-α degradation, followed by downregulating IL-6/JAK/STAT3 and XIAP gene levels." (PMID 34680295, 2021). "Simultaneously, they facilitate the adhesion between myeloma cells and BMSCs, stimulating increased production of IL-6 and RANKL." (PMID 33806209, 2021). "Myeloma cells exposed to IL-6 show increased STAT3 phosphorylation, which leads to the activation of genes involved in proliferation and survival." (PMID 33923357, 2021). "In vitro, neutralizing antibodies against IL-6 increase apoptosis and decrease growth in primary myeloma cells as well as IL-6-dependent and autocrine human myeloma cell lines." (PMID 33414408, 2021). "Studies have shown that stromal IL-15 production influences the growth of myeloma cells independently of IL-6, confirming the role of this cytokine in MM." (PMID 33808304, 2021). "The authors confirmed the ability of S100A9 to induce the secretion by myeloid-derived suppressor cell (MDSCs) of inflammatory and pro-myeloma cytokines including TNFα, IL-6, and IL-10." (PMID 34445745, 2021). "These fibroblast-like cells interact with MM cells, leading to the secretion of anti-apoptotic and myeloma growth-promoting cytokines, such as interleukin-6 (Il-6), insulin-like growth factor-1(IGF-1), and stromal cell-derived factor-1 (SDF-1)." (PMID 33842343, 2021). "Renal cells in rotating cell spinpods released significantly more GM-CSF in the presence of myeloma light chains from one donor, where as they release significantly more IL-6 in the presence of myeloma light chains from the other donor." (PMID 34716334, 2021). "Signal transducers and transcription activators 3 will target the miR-21 promoter according to bioinformatics analysis (STAT3); BBR can inhibit miR-21 transcription in multiple myeloma by downregulating IL-6 through STAT3 downregulation." (PMID 34885950, 2021). "Resveratrol was found to inhibit IL-6-induced activation of STAT3 in human multiple myeloma cells and endothelial cells." (PMID 34564613, 2021). "Gene ITGA4 along with ITGB1 codes for integrin VLA4 that mediates homing of myeloma cells into bone marrow and augment IL6 in the microenvironment." (PMID 34040057, 2021). "One such cytokine is IL-6, which is known to not only directly promote myeloma growth and survival, but also contributes to the expansion of pathogenic T helper 17 (Th17) cells." (PMID 33777050, 2021). "IGF-1 promotes growth and proliferation of myeloma cells via activation of the IGF-1 receptor in addition to IL-6." (PMID 33435539, 2021). "Further, aberrant JAGGED1 surface expression on multiple myeloma cells induces IL-6 secretion from surrounding bone marrow stromal cells, thus activating Notch." (PMID 34200313, 2021). "SASP proteins such as IL-6 can stimulate proliferation or drug resistance in myeloma cells, and thus targeting senescent bone marrow cells or senescence in general in the bone marrow niche represents a potential novel therapeutic target for MM patients." (PMID 33498240, 2021). "FGF2 is an angiogenic factor in multiple myeloma (MM) that positively regulates expression of growth and survival interleukin-6 (IL-6) in a reciprocal manner." (PMID 34068954, 2021).
myeloma (continued). "Exposure to fluid shear stress in combination with myeloma light chains increased the quantity of GM-CSF and IL-6 released even further, in a myeloma light chain donor-specific manner." (PMID 34716334, 2021). "The direct contact between the stromal cells and the myeloma cells demonstrated increased secretion of IL-6 by the stromal cells." (PMID 34201396, 2021). "IL−6 is one of the most well-known pro-myeloma adipokines, and targeting of IL6 signaling is under clinical investigation with monoclonal antibodies to IL−6 (siltuximab) or the IL−6 receptor (tocilizumab)." (PMID 33498240, 2021). "The first experience with the therapeutic use of anti-IL-6 antibodies dates back to 1988, when mouse anti-IL-6 was tested in patients with multiple myeloma." (PMID 34681685, 2021). "This has been confirmed by studies in which IL-6 stimulated the in vitro growth of fresh myeloma cells isolated from patients, while another study showed that anti-IL-6 antibodies had anti-tumour effects in MM." (PMID 33808304, 2021). "Within the bone marrow, multiple myeloma cells develop IL-6 independence from the surrounding stromal cells in a cell autonomous manner through Notch activation of the IL-6 gene." (PMID 34200313, 2021). "A recent study found another novel mechanism for metformin to block the IL-6 signaling pathway by decreasing IL-6R expression on multiple myeloma cells." (PMID 34881181, 2021). "In particular, retinoblastoma protein (pRB) seems to be constitutively phosphorylated in myeloma cells and interleukin 6 (IL-6) further shifts pRB to its phosphorylated form." (PMID 33923357, 2021). "Previous studies have indicated that the expression of CD45 in human myeloma cells is necessary for IL-6-induced proliferation." (PMID 34579758, 2021). "Incubation with the kinase inhibitor, singly or in combination, reduced the expression of MIP-1α, IL-12, IL-8, and IL-6 in MSCs cocultured with myeloma cells." (PMID 34150666, 2021). "ISL can inhibit the growth of human as well as murine myeloma cell lines via inhibiting IL-6 signaling (p-ERK, p-STAT3, etc.), inducing cell apoptosis and cell cycle arrest." (PMID 33401375, 2021). "Bortezomib blocks the activation of the NF-κB induced by TNF-α, leading to reduction of relations between multiple myeloma cells and bone marrow stromal cells and related decrease in secretion of IL-6, which supports their survival." (PMID 34205025, 2021). "In fact, IL-6 plays an important role in promoting myeloma cell growth and chemoresistance; increased IL-6 concentrations are associated with aggressive disease and poor outcome." (PMID 33198328, 2020). "In multiple myeloma, IL-6-activated STAT3 plays a major oncogenic role through the regulation of cell survival and proliferation." (PMID 32041604, 2020). "Many myeloma growth factors (MGFs) including interleukin (IL)-6 are known to be closely involved in the development of MM." (PMID 33014130, 2020). "On the other hand, myeloma cells are also known to produce their own IL-6 under an autocrine manner." (PMID 33014130, 2020). "Stromal and myeloma plasma cells, through autocrine stimulation of low doses of IL-1β, trigger IL-6 production, which in turn is responsible for the expansion and survival of myeloma cells." (PMID 32825489, 2020). "Interleukin-6 is the main growth and survival factor of myeloma cells and is over-produced in the form of paracrine by BMSCs in contact with myeloma cells." (PMID 31983174, 2020). "The IL-6-dependent human myeloma cell line INA-6 responds with a remarkably rapid and complete apoptosis to cytokine withdrawal." (PMID 32041604, 2020). "The phosphorylation of STAT3 was inhibited by auranofin through IL-6, leading to down-regulation of the anti-apoptotic proteins Mcl-1 and apoptosis of myeloma cells." (PMID 32695747, 2020).
myeloma (continued). "In marrow, PADI2 and PADI3 were elevated in some SARS-CoV-2 biopsies, and interestingly PADI2 was found to be elevated in marrow mesenchymal stem cells, which upregulates IL-6 via histone H3 deimination in multiple myeloma, contributing to chemo-resistance." (PMID 32629995, 2020). "A further study revealed that HO-1 attenuates IL-6-induced STAT3 phosphorylation in human keratinocyte HaCaT cells; however, high levels of HO-1 expression stimulated autocrine IL-6 production in human multiple myeloma U226 cells." (PMID 32204510, 2020). "Although MM subjects display augmented lipid peroxidation and lower concentrations of antioxidant enzymes in plasma and erythrocytes, research reported the effect of IL-6 in restoring intracellular redox homoeostasis in the setting of myeloma treatment." (PMID 33198328, 2020). "For example, an antibody against IL-6 has been tried in smoldering myeloma patients to delay MM progression." (PMID 32781681, 2020). "Multiple myeloma is highly dependent on cytokine signaling pathways, be it IL-6, other paracrine pathways, or direct cell: cell mediated contact with the stromal microenvironment." (PMID 32405334, 2020). "There are many signaling factors in MM patients that promote OC differentiation and activity, such as RANKL, chemokines (CCL3), IL-6, and myeloma-derived exosomes." (PMID 32937821, 2020). "We examined the effects of IL-6 exposure, a principle cytokine important for myeloma cell proliferation and survival, on tumor cells treated with MTX and PDX." (PMID 32405334, 2020). "The monoclonal anti-IL-6 antibody siltuximab showed anti-tumor effects against prostate cancer, renal cell cancer, and multiple myeloma." (PMID 32138303, 2020). "We discuss a case of a patient with multiple myeloma who was hospitalized with drug-induced ARDS who had a rapid response to an anti-interleukin-6 monoclonal antibody." (PMID 32774934, 2020). "IL-6 employment augmented myeloma cell resistance to substances that provoke oxidative stress, comprising IR and Dex (dexamethasone)." (PMID 33198328, 2020). "Myeloma patient-derived MSCs (MM-MSCs) also have alterations in the expression of transcripts involved in MM disease pathogenesis (IL-6) as well as impaired osteogenic capabilities." (PMID 33680918, 2020). "For the soluble factors, IL-6 is one of the most critical factors for myeloma cell survival, proliferation, and drug resistance." (PMID 32937821, 2020). "BM stromal cells have been reported as a major source of interleukin 6, which is a key player of inflammatory pathways in myeloma and inducer of hepcidin, which further emphasizes the importance of the abnormal ME." (PMID 33144847, 2020). "One such cytokine is interleukin-6 (IL6), which has roles in myeloma growth, survival, migration, and drug resistance." (PMID 33634031, 2020). "IL-6 is considered a growth factor for myeloma cells and is also an important regulator of inflammatory proteins." (PMID 32473631, 2020). "In Multiple Myeloma cells, adhesion to stromal cells through integrin β1, induce the release of IL-6 from BMSCs, most likely as a result of induction of NF-κB signalling." (PMID 32098106, 2020). "MitoSOX Red staining demonstrated that IL-6 administration reduced late mitochondrial oxidant generation in irradiated myeloma cells." (PMID 33198328, 2020). "The production of VEGF in the bone marrow environment is upregulated by myeloma cell adhesion to BMSCs and by IL-6." (PMID 33014130, 2020). "IL-6 has a role in the development of multiple myeloma, as demonstrated by its ability to induce apoptosis by blocking the IL-6R/STAT3 pathway in vitro and the resistance of the IL-6 -/- mouse to the induction of plasmacytoma." (PMID 32283655, 2020). "In turn, osteoclasts secrete IL6 to stimulate proliferation and growth of not only myeloma cells but other osteoclasts as well." (PMID 33634031, 2020).